MMP9 (matrix metallopeptidase 9)
Diseases named in the same sentence as MMP9 in open-access papers (continued):
Sharing a sentence is not in itself a finding about the gene and the disease.
glaucoma (47 papers, 2008 to 2026). Increased pressure in the eyeball due to obstruction of the outflow of aqueous humor. "We found that the MMP3 rs3025058 TT genotype was associated with more advanced glaucoma and a higher C/D ratio in the additive and dominant models, while the MMP9 rs520544 CC genotype was marginally associated with a thicker CCT." (PMID 39769228, 2024). "Meta-analyses revealed an increased risk of glaucoma associated with the MMP1 rs1799750 polymorphism and a possible protective role of the MMP9 rs17576 G>A polymorphism against the development of glaucoma in the Caucasian population." (PMID 39769228, 2024). "In yet another recent meta-analysis, MMP9 rs17576 G > A polymorphism was observed to be a protective factor against the development of glaucoma." (PMID 29432439, 2018). "Assessing the role of other SNPs in the gene can allow for more powerful haplotype analysis to better elucidate the role of MMP9 variants as a genetic risk factor for glaucoma." (PMID 29432439, 2018). "Numerous studies have linked changes in the expression of MMP9 in the retina, optic nerve, aqueous humor, and TM with glaucomatous eyes in humans and animal models of glaucoma." (PMID 29432439, 2018). "The subgroup analysis according to ethnicity demonstrated a significant protective association between the MMP-9 rs17576 G > A polymorphism and glaucoma susceptibility in the Caucasian population." (PMID 28431514, 2017). "Overall, our analysis indicated that MMP-9 polymorphisms (rs17576 G > A and rs3918249 C > T) conferred different significantly susceptibility to glaucoma." (PMID 28431514, 2017). "With regards to MMP-9 gene polymorphisms and glaucoma risk, 9 articles (reporting a total of 11 case–control studies) involving 2,028 cases and 1,794 controls were included in our analyses of the 6 most commonly reported SNP loci." (PMID 28431514, 2017). "BAK treatment appeared to cause elevated levels of MMP-9, a matrix metalloproteinase implicated in the pathogenesis of glaucoma." (PMID 21750606, 2011). "MMP1, MMP2, and MMP9 have previously been implicated in the pathogenesis of primary open angle glaucoma (POAG) and open angle glaucoma secondary to exfoliation syndrome (XFG), respectively." (PMID 20808730, 2010). "The association studies became focused on the effects of MMP-9 on glaucoma." (PMID 35647299, 2022). "In addition, the analysis of MMP9 demonstrated the ability of VGLCR to restore the alteration of the composition of the extracellular matrix caused by glaucoma, both in RGC and in eyecup preparations." (PMID 34441662, 2021). "That MMP9 may have a causal role in RGCs death was shown in a rat glaucoma model wherein the neuroprotection conferred by pyrrolidine dithiocarbamate (PDTC) to RGCs was mediated by downregulation of Mmp9." (PMID 29432439, 2018). "Sex specific differences in genetic susceptibility to glaucoma could be accounted by the effect of estrogens on the levels of proinflammatory cytokines like IL-1beta which is known to induce MMP9 expression in primary and immortalized cells." (PMID 29432439, 2018). "Our meta-analysis demonstrates that MMP-9 rs17576 G > A polymorphism might be a protective factor against the development of glaucoma in Caucasian population." (PMID 28431514, 2017). "Significant associations were only found between MMP-9 rs17576 G > A polymorphism (GA vs. GG: OR = 0.80, 95%CI = 0.67-0.97, P = 0.02, I2 = 0%), MMP-9 rs3918249 C > T polymorphism (TT vs. CC + CT: OR = 0.71, 95%CI = 0.51-0.98, P = 0.04, I2 = 0%) and glaucoma risk in the general population." (PMID 28431514, 2017). "In conclusion, our meta-analysis indicated that the MMP-9 rs17576 G > A polymorphism maybe an important protective factor against glaucoma, especially in the Caucasian population." (PMID 28431514, 2017).
glaucoma (continued). "Genetic variants in the MMP9 gene, specifically cis-regulatory elements which provide a binding site for transcription factors, can influence its expression and hence may modify overall genetic risk for glaucoma onset or progression." (PMID 29432439, 2018). "Specifically, one study observed a 25% decrease in MMP-9 levels after six weeks of timolol therapy in patients with glaucoma." (PMID 40698094, 2025). "On the contrary, only 27.27% of glaucoma patients treated with Latanoprost PF eye drops and 8.33% of the control group revealed elevated levels of MMP-9 in the tear film." (PMID 37959198, 2023). "MMP-3 and MMP-9 are 2 members of this enzyme group, and their presence has been found to be particularly influenced by the presence of glaucoma." (PMID 37233995, 2023). "The involvement of MMPs, especially MMP-9, in the pathogenesis of various glaucoma types has been studied and discussed." (PMID 37511830, 2023). "A dual-functional smart CL sensor utilizing optical-based technology has been developed for IOP monitoring and detecting matrix metalloproteinase-9 (MMP-9), which is an important biomarker in glaucoma." (PMID 37919748, 2023). "MMP-3 and MMP-9 are two members of this enzyme group that have been shown to be particularly affected in patients with glaucoma." (PMID 37233995, 2023). "MMP-9, whose expression and activity in glaucoma are mainly upregulated during the early stages of the disease, helps maintain the ultrastructural organization of the trabecular meshwork." (PMID 35457074, 2022). "A clinical study found that more glaucoma patients on BAK-preserved PGAs had elevated MMP9 in tears (>40 ng/mL) compared with those on BAK-free tafluprost (46.7% vs. 16.7%;p < 0.05)." (PMID 36345493, 2022). "An explanation should be added for the special increase in MMP-9 in tear samples of glaucoma patients." (PMID 35628448, 2022). "Both healthy controls and other pathologies groups presented MMP-9 concentrations mainly below the threshold; contrarily, the cataracts and glaucoma groups presented tear MMP-9 values mostly over 30 ng/mL." (PMID 35628448, 2022). "The presented results preliminarily validated the functionality of the AbMA assay, not only in quantifying MMP-9 but also in being able to monitor the inflammatory response resulting from BAK-preserved eye drop treatments in glaucoma patients." (PMID 35628448, 2022). "On the other hand, elevated concentrations of TIMP-4, a known inhibitor of MMP-9, have been confirmed in the aqueous humor of the patients with primary open-angle glaucoma, which would also disrupt the MMP/TIMP molar ratio." (PMID 35457074, 2022). "A significant elevation of MMP-9 concentration in the tears of glaucoma patients compared with healthy controls was observed." (PMID 35628448, 2022). "Increased tear MMP-9 activity was observed in all glaucoma groups at early stages of the disease, and in PES subjects was higher than in control and advanced glaucoma, suggesting activation of the extracellular matrix in the early stages of the disease." (PMID 34439995, 2021). "We found the activity of MMP-9 getting significantly reduced in PXG compared to other forms of glaucoma suggesting exhaustion of degradatory mechanisms in late stages of the disease." (PMID 33914756, 2021). "In this study we found TGFβ1 and MMP-9 protein concentrations were high in PXG but MMP-9 activity was reduced in eyes with glaucoma." (PMID 33914756, 2021). "Objective assessment of dry eye disease (DED) severity and ocular inflammation using the InflammaDry® test for extracellular matrix metalloproteinase-9 (MMP-9) and the impact of antiglaucoma eye drops in people with primary open-angle glaucoma (POAG)." (PMID 31073413, 2019). "The present study examined the association of -1562C>T promoter polymorphism in the MMP9 gene with Primary Open Angle Glaucoma (POAG) and Primary Angle Closure Glaucoma (PACG) in a north Indian population." (PMID 29432439, 2018).
glaucoma (continued). "Subgroup analysis also suggested that MMP-9 rs17576 G > A was related to glaucoma in the Caucasian population (GA vs. GG: OR = 0.67, 95%CI = 0.45-1.00, P = 0.05; GA + AA vs. GG: OR = 0.66, 95%CI = 0.45-0.97, P = 0.03, I2 = 0%)." (PMID 28431514, 2017). "Clinical Relevance of MMPs as Biomarkers: Elevated levels of specific matrix metalloproteinases (MMPs), particularly MMP-2 and MMP-9, may serve as potential biomarkers for the progression of glaucoma." (PMID 40698094, 2025). "Our results suggest that systemic MMP-9 may still play a role in glaucoma pathogenesis despite normal AqH levels." (PMID 41154592, 2025). "Interestingly, compared to Polyquad®, BAK has been shown to be associated with dose-dependent reductions in TM cell viability and increased levels of MMP-9, a factor in glaucoma pathogenesis." (PMID 39451386, 2024). "IOP could be monitored by observing structural color changes, and glaucoma could be predicted using quantitative SERS measurement of MMP-9 levels in tear film." (PMID 38391624, 2024). "An association between increased MMP-9 levels, apoptosis, and increased IOP in glaucoma was found." (PMID 37511830, 2023). "Similarly, the concentration of MMP-9 in the AH was higher in the glaucoma group compared to the control group (p < 0.05, unpaired t-test)." (PMID 37511830, 2023). "Similar results were described by Kim and coworkers when they reported that approximately 72% of glaucoma patients displayed a high concentration of tear MMP-9 (over 40 ng/mL); however, when studying a control group of 47 healthy subjects, only about 32% of them showed an increase in this biomarker." (PMID 35628448, 2022). "Therefore, an optical‐based dual‐functional smart contact lens sensor has been introduced to monitor intraocular pressure (IOP) and detect matrix metalloproteinase‐9 (MMP‐9), both of which are key biomarkers in many eye‐related diseases such as glaucoma." (PMID 35195359, 2022). "However, 75% and 83% of patients in the glaucoma and cataract groups, respectively, had a tear MMP-9 concentration above the pathological threshold of 30 ng/mL, denoting ocular surface inflammation." (PMID 35628448, 2022). "This hypothesis is strengthened when taking notice of P9, the glaucoma patient with the highest value of MMP-9 concentration in tear, who was under the treatment of two different BAK-preserved prostaglandin analogues." (PMID 35628448, 2022). "Our results showed that there is an increase of TGFβ1 and MMP-9 which was consistent in each ocular tissue in the later stages of PXF which may have role in the pathogenesis of glaucoma." (PMID 33914756, 2021). "How activated MMP-9 is regulated in each stage of PXF may hold the key for correcting the aberrant ECM deposition and fibrosis seen in later stages causing glaucoma." (PMID 33914756, 2021). "Significant differences in the frequencies of the MMP-9 rs17576 G > A SNP genotypes were found between the glaucoma and healthy control groups, which suggested an increased risk for glaucoma in the Chinese population according to a dominant model (OR = 2.84, 95%CI = 1.63-5.64, P = 0.03)." (PMID 28431514, 2017). "Shorter axial length observed in patients with primary angle closure glaucoma (PACG) might be due to altered matrix metalloproteinase-9 (MMP9) activity resulting in ECM remodeling during eye growth and development." (PMID 27272641, 2016). "We therefore postulate that the mechanisms underlying RGC death in the NMDA-induced glaucoma model and in the optic nerve ligation/crush models are very distinct and that MMP-2 and MMP-9 are apparently differentially involved in these different types of glaucomatous injury." (PMID 26451076, 2015). "Previous studies have shown that MMP-2 and MMP-9 may play major roles in the pathogenesis of steroid induced glaucoma as their levels were decreased in human TM cells treated with steroid." (PMID 23977299, 2013).
glaucoma (continued). "Furthermore, in a rodent glaucoma model optic nerve ligation led to significantly increased MMP9 concentrations in the retina." (PMID 20808730, 2010). "Metalloproteinases (MMP-2 and MMP-9) are upregulated in the optic nerve head of glaucoma patients." (PMID 18334938, 2008). "In terms of the glaucoma phenotype, we found that the MMP3 rs3025058 TT genotype was associated with more advanced glaucoma and a higher C/D ratio in the additive and dominant models, while the MMP9 rs520544 CC genotype was marginally associated with a thicker CCT." (PMID 39769228, 2024). "In addition, MMP-9 may promote pathological apoptosis by the activation of cell death receptors and pro-apoptotic proteins in absolute glaucoma." (PMID 35457074, 2022). "For example, the R279Q variant of MMP-9 (rs17576 G>A) was reported to be protective against the development of glaucoma in a Caucasian population, and MMP-9 rs3918249 C/C instead of C/T genotype in the promoter region was more frequent in glaucoma and AMD patients." (PMID 31398819, 2019). "Overall, significant associations were only found between MMP-9 rs17576 G > A polymorphism (GA vs. GG: OR = 0.80, 95%CI = 0.67-0.97, P = 0.02, I2 = 0%), MMP-9 rs3918249 C > T polymorphism (TT vs. CC + CT: OR = 0.71, 95%CI = 0.51-0.98, P = 0.04, I2 = 0%) and glaucoma risk." (PMID 28431514, 2017). "Additionally, MMP-9 plays an important role in maintaining IOP, and further investigation into the mechanisms of MMP-9 activity in the anterior angle may give clues to how extracellular matrix remodeling participates in ocular hypertension and glaucoma." (PMID 23559862, 2013). "Increased MMP Expression in Glaucoma: Numerous studies have reported that glaucoma patients exhibit elevated levels of specific matrix metalloproteinases (MMPs), particularly MMP-2 and MMP-9, within the aqueous humor and trabecular meshwork." (PMID 40698094, 2025). "On the contrary, 27.27% of the glaucoma patients receiving Latanoprost PF showed MMP-9 overexpression and only 8.33% of the control group revealed MMP-9 overexpression." (PMID 37959198, 2023). "In order to assess the severity of the disease, such as glaucoma, simultaneous and quantitative analysis of both IOP and MMP‐9 is required." (PMID 35195359, 2022). "MMP-9 is one such key molecule involved in ECM degradation and its role as a tear-based predictive marker for glaucoma has already been suggested in our previous study." (PMID 33914756, 2021). "Our own study showed decreased tear MMP-9 activity in severe glaucoma and PXG eyes compared to other forms of primary glaucoma supporting an important role of MMP-9 in glaucoma onset in PXF." (PMID 33914756, 2021). "Among different MMPs, MMP9 encodes a 92-kDa multidomain zinc dependent enzyme known as gelatinase or type V collagenase and is known to extensively affect ECM deposition and turnover in the TM and LC regions in glaucoma." (PMID 29432439, 2018). "The up-regulation of several MMPs specifically MMP-2, MMP-9, and MMP-13 are reported in steroid induced mice model of glaucoma." (PMID 25988186, 2015). "In animal models of glaucoma, MMP-9 in the retina had a negative impact on retinal ganglion cell survival, while the function of other MMPs is less known." (PMID 39769228, 2024). "Also, changes in MMP-9 activity in the AH and tear samples of patients with POAG and early forms of primary angle-closure glaucoma (PACG) and POAG eyes compared to controls have been reported." (PMID 37511830, 2023). "For MMP-9, the inflammatory response in DED can affect the expression and activity of MMPs, which may have downstream effects on the extracellular matrix remodeling in the trabecular meshwork in glaucoma." (PMID 37511830, 2023). "In addition, in our study, IOP was not increased for the glaucoma group, but increased MMP-9 was found in the AH of POAG patients." (PMID 37511830, 2023).
glaucoma (continued). "Moreover, it has been demonstrated that the MMP-9 null mice had aberrant collagen composition of the trabecular meshwork, as well as lowered aqueous humor turnover and ocular hypertension, indicating that MMP-9 may be an important remodeler of trabecular meshwork mitigating the course of glaucoma." (PMID 35457074, 2022). "We also found an increased expression of MMP-2, MMP-3, MMP-9, TGFβ-1, and TGFβ-3 in eyes with JIAU, independent of the presence of glaucoma." (PMID 29675026, 2018). "In another study, mRNA expression of MMP-1 (but not MMP-2, MMP-9, and MMP-13) was found to be significantly up-regulated in steroid induced sheep model of glaucoma." (PMID 25988186, 2015). "Elevated FN1 levels with reducing MMP-9 activity despite increased TGF levels in severe disease stages suggest an escape of the downstream ECM related pathways and alternate control by non-canonical pathways as glaucoma sets in." (PMID 33914756, 2021).